SSTR4 (somatostatin receptor 4)
Description:
Receptor for somatostatin-14. The activity of this receptor is mediated by G proteins which inhibits adenylyl cyclase. It is functionally coupled not only to inhibition of adenylate cyclase, but also to activation of both arachidonate release and mitogen-activated protein (MAP) kinase cascade. Mediates antiproliferative action of somatostatin in tumor cells.
Synonyms: SS-4-R; SS4-R; SS4R; SST4
Tractability: Small molecule: a structure with a bound ligand is known; a high-quality ligand is known; it belongs to a druggable protein family. Antibody: its Gene Ontology location is reachable by antibodies, with high confidence; UniProt places it where antibodies can reach, with medium confidence; UniProt predicts a signal peptide or a membrane-spanning region. PROTAC: a small molecule that binds it is known. Other modalities: an approved drug acts on it.
Target class: Peptide receptor (family A GPCR); Membrane receptor; Short peptide receptor (family A GPCR); Family A G protein-coupled receptor; Somatostatin receptor
Chemical probes: CHEMBL3421842
Gene: Protein-coding gene on chromosome 20 (23,035,312 to 23,039,237, forward strand). Ensembl gene ENSG00000132671.
Subcellular location: Cell membrane
Pathways (Reactome):
Signal Transduction: G alpha (i) signalling events; Peptide ligand-binding receptors
Gene Ontology:
Molecular function: protein binding; neuropeptide binding; somatostatin receptor activity; G protein-coupled receptor activity
Biological process: cellular response to glucocorticoid stimulus; G protein-coupled receptor signaling pathway; G protein-coupled receptor signaling pathway, coupled to cyclic nucleotide second messenger; negative regulation of cell population proliferation; neuropeptide signaling pathway; somatostatin signaling pathway
Cellular component: neuron projection; plasma membrane; membrane
Genetic constraint (gnomAD): Missense variants: 644 observed, 522.3 expected, observed/expected ratio (o/e) 1.23, 90% interval 1.15 to 1.32. Synonymous variants: 272 observed, 242.63 expected, observed/expected ratio (o/e) 1.12, 90% interval 1.01 to 1.24.
Homologues: Orthologues: chimpanzee SSTR4 (99% identical), macaque SSTR4 (95% identical), mouse Sstr4 (88% identical), rat Sstr4 (88% identical), tropical clawed frog sstr4 (65% identical), Caenorhabditis elegans trhr-1 (23% identical), Drosophila melanogaster Rh7 (21% identical). Paralogues in human: SSTR1 (58% identical), SSTR5 (45% identical), SSTR2 (41% identical), SSTR3 (41% identical), OPRD1 (37% identical), OPRK1 (34% identical), OPRL1 (33% identical), OPRM1 (32% identical), NPBWR2 (31% identical), NPBWR1 (29% identical), KISS1R (27% identical), CMKLR2 (26% identical), and 5 more.